NRDC (nardilysin convertase)
Description:
Cleaves peptide substrates on the N-terminus of arginine residues in dibasic pairs. Is a critical activator of BACE1- and ADAM17-mediated pro-neuregulin ectodomain shedding, involved in the positive regulation of axonal maturation and myelination. Required for proper functioning of 2-oxoglutarate dehydrogenase (OGDH) (By similarity).
Synonyms: NRD1; hNRD1; hNRD2
Tractability: Antibody: UniProt predicts a signal peptide or a membrane-spanning region. PROTAC: ubiquitination databases record sites on it.
Target class: Enzyme; Hydrolase
Gene: Protein-coding gene on chromosome 1 (51,787,517 to 51,878,805, reverse strand). Ensembl gene ENSG00000078618.
Subcellular location: Mitochondrion; Cell projection, dendrite
Subcellular location (Human Protein Atlas): Nucleoplasm
Gene Ontology:
Molecular function: endopeptidase activator activity; protein binding; epidermal growth factor binding; metalloendopeptidase activity; metal ion binding
Biological process: positive regulation of membrane protein ectodomain proteolysis; positive regulation of tumor necrosis factor production; positive regulation of tumor necrosis factor-mediated signaling pathway; negative regulation of cold-induced thermogenesis; positive regulation of axonogenesis; positive regulation of myelination; proteolysis
Cellular component: mitochondrial matrix; mitochondrion; cell surface; cytosol; dendrite
Genetic constraint (gnomAD): Loss-of-function variants: 34 observed, 89.98 expected, observed/expected ratio (o/e) 0.38, 90% interval 0.29 to 0.5. The upper end of that interval is the gene's LOEUF score, 0.5, which puts it in group 2 of 6, group 1 being the genes least tolerant of losing a copy. Missense variants: 774 observed, 1,010.9 expected, observed/expected ratio (o/e) 0.77, 90% interval 0.72 to 0.81. Synonymous variants: 333 observed, 378.43 expected, observed/expected ratio (o/e) 0.88, 90% interval 0.8 to 0.96.
Homologues: Orthologues: chimpanzee NRDC (99% identical), macaque NRDC (99% identical), rabbit NRDC (96% identical), pig NRDC (95% identical), dog NRDC (94% identical), guinea pig NRDC (94% identical), rat Nrdc (93% identical), mouse Nrdc (93% identical), zebrafish nrd1a (67% identical), tropical clawed frog nrdc (60% identical), zebrafish nrd1b (59% identical), Drosophila melanogaster Nrd1 (31% identical), and 2 more. Paralogues in human: IDE (31% identical), PITRM1 (13% identical), PMPCB (10% identical), UQCRC1 (9% identical), PMPCA (8% identical), UQCRC2 (8% identical).
Diseases named in the same sentence as NRDC in open-access papers:
NRDC is named in the same sentence as 27 diseases in open-access papers, as found by Europe PMC text mining. Sharing a sentence is not in itself a finding about the gene and the disease. The quoted sentences say what the papers report.
gastric cancer (2 papers, 2017 to 2022). A primary or metastatic malignant neoplasm involving the stomach. "NRDC has recently been revealed to be involved in the tumorigenesis of various types of cancer, including intrahepatic cholangiocarcinoma, malignant cerebral infarction, esophageal squamous cell carcinoma, and gastric cancer." (PMID 35683488, 2022). "Knockdown of NRDC attenuates gastric cancer cell growth both in vitro and in a xenograft model." (PMID 28230087, 2017). "In this respect, we previously demonstrated that NRDC regulates activation of TNF-α and subsequent production of inflammatory cytokines in gastric cancer cells." (PMID 28230087, 2017).
chronic pancreatitis (1 paper, 2022). A chronic inflammatory process causing damage and fibrosis of the pancreatic parenchyma. "Meanwhile, a report revealed that when NRDC is knocked out in mice, it leads to spontaneous chronic pancreatitis, diabetes, and the stimulation of pancreatic ductal adenocarcinoma initiation." (PMID 35683488, 2022).
colorectal cancer (1 paper, 2022). A primary or metastatic malignant neoplasm that affects the colon or rectum.
diabetes (1 paper, 2022). "Nine diabetes-associated genes that had direct interactions with ten HLHS candidates were responsible for this enrichment, including the novel interaction of the diabetes-associated IRS1 with the HLHS candidate NRDC." (PMID 35456433, 2022).
pancreatic ductal adenocarcinoma (1 paper, 2022). An infiltrating adenocarcinoma that arises from the epithelial cells of the pancreas. "Further bioinformatics analysis revealed that NRDC correlated with proliferation and migration pathways; in particular, it mediated cell-matrix adhesion-dependent activation in pancreatic ductal adenocarcinoma." (PMID 35683488, 2022). "Compared with the control group, the expression of NRDC was decreased in different pancreatic ductal adenocarcinoma cell lines." (PMID 35683488, 2022). "Although a significant effect of NRDC on pancreatic ductal adenocarcinoma pathobiology is evident, its clinical significance in other cancer types remains poorly elucidated." (PMID 35683488, 2022). "A normal pancreatic cell line, HPDE, was treated as a control group for pancreatic ductal adenocarcinoma cell lines to measure the transcriptional level of NRDC by qRT-PCR." (PMID 35683488, 2022). "However, the expression profiles and biological relevance of NRDC in pancreatic ductal adenocarcinoma have rarely been reported." (PMID 35683488, 2022). "As expected, NRDC was enriched in a number of important signaling pathways, such as focal adhesion, cell cycle, proliferation, autophagy, type I diabetes, and apoptosis pathway activation in pancreatic ductal adenocarcinoma." (PMID 35683488, 2022). "Additionally, experiments in vitro and in vivo were deemed necessary to further confirm the biological activity of NRDC in pancreatic ductal adenocarcinoma." (PMID 35683488, 2022). "In order to verify the NRDC transcriptional level in pancreatic ductal adenocarcinoma cell lines." (PMID 35683488, 2022). "In other words, the expression of NRDC may be negatively correlated with the clinical stage and grade in pancreatic ductal adenocarcinoma." (PMID 35683488, 2022). "Hence, in order to determine the role of NRDC in pancreatic ductal adenocarcinoma, we designed an observational cohort study to determine the clinical value of NRDC." (PMID 35683488, 2022). "Furthermore, RT-PCR and immunohistochemistry demonstrated that NRDC was not only decreased in different pancreatic ductal adenocarcinoma cell lines but also decreased in patients’ PDAC tissues." (PMID 35683488, 2022). "Consequently, we wondered whether NRDC is an excellent tumor marker to evaluate the TNM staging and histopathological grading of pancreatic ductal adenocarcinoma." (PMID 35683488, 2022).
rheumatoid arthritis (1 paper, 2024). A chronic, systemic autoimmune disorder characterized by inflammation in the synovial membranes and articular surfaces. "Given the role of NRDC in the activation of TNF-alpha, which was validated in some inflammatory disease models including rheumatoid arthritis and steatohepatitis, NRDC may aggravate the pathology of ACS by enhancing inflammation." (PMID 38233578, 2024).
schizophrenia (1 paper, 2024). A major psychotic disorder characterized by abnormalities in the perception or expression of reality. "Furthermore, the density of NRDC immunoreactive neurons was nearly 50 % higher in the bilateral prefrontal areas of postmortem patients with schizophrenia." (PMID 38694089, 2024). "The low levels of plasma NRDC observed among patients with schizophrenia may be related to these neurodevelopmental abnormalities." (PMID 38694089, 2024). "However, logistic regression analysis revealed higher levels of l-serine and homocysteine, but lower levels of d-serine and NRDC in patients with schizophrenia compared to those in controls." (PMID 38694089, 2024). "However, whether NRDC expression is altered in the living brain of patients with schizophrenia remains unclear." (PMID 38694089, 2024). "In contrast, the low level of NRDC observed in our study infers an interesting relationship between NRG1 and schizophrenia." (PMID 38694089, 2024). "Moreover, plasma l-serine level was found to be correlated with plasma NRDC level in healthy controls, suggesting a link between NMDA receptor hypofunction and myelination deficits in the pathogenesis of schizophrenia." (PMID 38694089, 2024). "Furthermore, NRG1 is involved in the mechanisms by which NRDC controls myelin sheath formation, and one study proposed that NRG1 may be involved in the pathogenesis of schizophrenia." (PMID 38694089, 2024). "Plasma NRDC and l-serine concentrations were found to be significantly correlated among healthy controls, but not in patients with schizophrenia, suggesting that some relationships between myelin formation and NMDA receptor function may be disrupted in schizophrenia." (PMID 38694089, 2024).
type I diabetes (1 paper, 2022). "Kyoto Encyclopedia of Genes and Genomes (KEGG) examination showed that NRDC is enriched in several interesting pathways, such as focal adhesion, PI3K-Akt pathway, pancreatic secretion, and type I diabetes." (PMID 35683488, 2022).
tumor (5 papers, 2018 to 2025). "The first was a group of novel genes and the second was a group of genes associated with various cancer and tumour diseases (TXNDC12, NRDC, MIR761, ITSN2, NCOA1, SCUBE2, DENND5A, RCN2)." (PMID 40003092, 2025). "Stable expression of NRDC in PATC148 cells with Dox-induced expression of p72Plk3 resulted in slower tumor growth in an orthotopic xenograft mouse model." (PMID 38605037, 2024). "After the χ2 test, we found that the expression of NRDC was significantly associated with TNM stage (p = 0.011), differentiation (p < 0.001), metastasis (p < 0.001), and tumor size (p < 0.001)." (PMID 35683488, 2022). "Moreover, we found that the expression of NRDC was negatively correlated with tumor size, metastasis, differentiation, and TNM staging in patients." (PMID 35683488, 2022). "Moreover, elevated serum level of nardilysin (N-arginine dibasic convertase, NRDC), a soluble cytosolic protein, correlated with increased NRDC mRNA expression in tumor tissue and EMT-inducing transcription factors, and was associated with shorter OS and DFS in patients with iCCA." (PMID 35205774, 2022).
cancer (3 papers, 2020 to 2025). A tumor composed of atypical neoplastic, often pleomorphic cells that invade other tissues. "Compared with cancer tissue, the expression level of NRDC is highly expressed in normal tissue." (PMID 35683488, 2022).
NRDC also shares sentences with these, for which no sentence is quoted: pancreatic cancer (2 papers); acute pericarditis (1); cardiovascular diseases (1); cholangiocarcinoma (1); chronic gastritis (1); congestive heart failure (1); esophageal squamous cell carcinoma (1); gastric tumors (1); gastritis (1); infection (1); intrahepatic cholangiocarcinoma (1); liver fibrosis (1); metastatic melanoma (1); motor neuron degeneration (1); pneumonia (1); steatosis (1); Takotsubo syndrome (1).